SNORD12C (small nucleolar RNA, C/D box 12C)
Synonyms: U106; E2; E2-1; E3; RNU106; SNORD106
Gene: Small nucleolar RNA gene on chromosome 20 (49,278,940 to 49,279,028, forward strand). Ensembl gene ENSG00000209042.
Gene Ontology:
Biological process: RNA processing
Cellular component: nucleolus
Homologues: Orthologues: chimpanzee SNORD12C (100% identical), macaque SNORD12C (100% identical), rat Snord12c (90% identical), dog SNORD12C (88% identical), pig SNORD12C (87% identical), guinea pig SNORD12C (85% identical), mouse Gm25878 (84% identical), rabbit SNORD12C (82% identical). Paralogues in human: SNORD12B (71% identical), SNORD12 (69% identical).
Diseases named in the same sentence as SNORD12C in open-access papers:
SNORD12C is named in the same sentence as 4 diseases in open-access papers, as found by Europe PMC text mining. Sharing a sentence is not in itself a finding about the gene and the disease. The quoted sentences say what the papers report.
colorectal cancer (1 paper, 2021). A primary or metastatic malignant neoplasm that affects the colon or rectum. "In colorectal cancer, ribomethylation levels at 28S-Gm3899(3878) and 28S-Gm4623(4593) are increased via concomitant stabilization of SNORD12C and SNORD78 snoRNP complexes by the SNORD12C host gene encoding the lncRNA ZFAS1." (PMID 34775914, 2021).
SNORD12C also shares sentences with these, for which no sentence is quoted: cancer (1 paper); colon cancer (1); tumor (1).